TH (tyrosine hydroxylase)
Diseases named in the same sentence as TH in open-access papers (continued):
Sharing a sentence is not in itself a finding about the gene and the disease.
Parkinson disease (continued). "Stromberg study also suggests a protective response by enhancement in the recovery of striatal dopamine tyrosine hydroxylase (TH) positive fibers and TH positive neurons in the substantia nigra pars compacta in experimental rat induced Parkinsonism after feeding with spirulina." (PMID 26306668, 2015). "These authors linked their findings with a physiological need for Fe(II) in dopamine synthesis through tyrosine hydroxylase and with a pathological scenario, involving the participation of Fe(II) in the Fenton reaction, increasing the oxidative stress of Parkinson's disease." (PMID 24672633, 2014). "In order to verify MPTP-injection impact on nigrostriatal system (classically affected in Parkinson’s disease) and validate our experimental model, we quantified the number of dopaminergic neurons by immunostaining of tyrosine hydroxylase (TH) (limiting enzyme in dopamine synthesis)." (PMID 23741377, 2013). "This distinct difference in how TH may regulate DA between striatum and SN may be of significant consequence in models of Parkinson's disease and aging, wherein locomotor dysfunction may be related to deficient DA regulation." (PMID 22242182, 2012). "TH immunohistochemistry is considered the most reliable method to identify dopaminergic cells in the human striatum, both in normal control individuals and Parkinson's disease patients." (PMID 22272358, 2012). "In an acute mouse model of Parkinsonism induced by MPTP, treadmill exercise ameliorates behavioral deficits and reverses several striatal dopaminergic indices including the loss of DA, TH-immunoreactivity, and DA transporter levels when compared to the sedentary Parkinsonian animals." (PMID 19154608, 2009). "If TH loss does not occur in striatum during aging, it is possible that either decreased striatal TH activity may contribute to Parkinsonism, or decreased TH protein or activity in another DA region is the source of Parkinsonism." (PMID 20037632, 2009). "Because abnormal expression of TH is related to dopaminergic dysfunction such as in Parkinson's disease, TH may be a key molecule in dopaminergic function." (PMID 19500377, 2009). "A tyrosine hydroxylase (TH) expression plasmid was delivered to the striatum of adult rats using PEG immunoliposome nanoparticles in order to normalize TH expression levels in the 6-hydroxydopamine rat model of Parkinson's disease." (PMID 19091001, 2008). "Lack of TH immunolabeling is suggested to be a morphological indicator of dopaminergic cell loss during the induction of Parkinson’s symptoms in both vertebrates and invertebrates such as Drosophila flies, the pond snail Lymnaea stagnalis, and the worm Lumbricus terrestris." (PMID 39000265, 2024). "These cells express mOrange as a fluorescent marker inserted at the last exon of the TH gene, enabling live imaging and isolation of dopaminergic neurons crucial for studying Parkinson disease (PD) research and other neurodegenerative disorders." (PMID 39456792, 2024). "The study mainly explored whether Safranal improved the pathological symptoms of Parkinson’s disease mouse, increased the expression of TH and DA content in Striatum, to clarified the relevant mechanisms, which provide a new treatment way for clinical Parkinson’s disease." (PMID 38683404, 2024). "However, previous studies have suggested that inducing TH expression in astrocytes may prevent Parkinsonism in rats." (PMID 38245794, 2024). "In addition, kukoamine A improved gross motor function and neuronal activity in a Parkinson's disease model, increased the number of tyrosine hydroxylase (TH)-positive cells in the substantia nigra (SN) and striatum (Str), and decreased the expression of alpha-synuclein in the brain." (PMID 39473702, 2024).
Parkinson disease (continued). "Our findings suggest that enhancing cyclic nucleotide signalling—whether via PDE inhibition or GUCY2C activation—holds considerable promise for treating Parkinson’s disease by boosting endogenous dopamine production through tyrosine hydroxylase Ser40 phosphorylation." (PMID 39456033, 2024). "In the same Parkinson's disease model, apigenin has been shown to modulate dopaminergic neurotransmission by downregulating α-synuclein expression and enhancing dopamine biosynthesis through the upregulation of dopamine D2 receptor protein expression and tyrosine hydroxylase." (PMID 37901424, 2023). "Furthermore, more than 50% of VHL transgenic NSCs transplanted into Parkinson’s disease rat models not only differentiated into tyrosine hydroxylase (TH)-positive dopamine-producing cells but also showed a marked reduction in apomorphine-induced turnover in behavioral analysis." (PMID 36835292, 2023). "Furthermore, a 100% increase of TH-positive neurons is reported in the OB tissue of Parkinson’s patients, which may be responsible for the hyposmia in these patients." (PMID 37970447, 2023). "In previous studies in a subchronic mouse model of Parkinson’s disease induced by 1-methyl-4-phenyl-1,2,3,6-tetrahydropyridine, Mucuna pruriens seed extract was not able to prevent 1-methyl-4-phenyl-1,2,3,6-tetrahydropyridine-induced tyrosine hydroxylase reduction or microglia activation." (PMID 37299465, 2023). "Previous studies revealed that expression of the gene encoding nigrostriatal tyrosine hydroxylase (TH), a rate-limiting enzyme of dopamine biosynthesis, is reduced in Parkinson’s disease and dopa-responsive dystonia; however, the mechanism of TH depletion in these disorders remains unclear." (PMID 32471089, 2020). "Altogether, the enhancement of tyrosine hydroxylase in naïve dopaminergic cells and the protective effects in a cellular model of Parkinson’s disease suggest that full-length Nurr1 fusion protein may contribute to the development of a novel concept of protein-based therapy." (PMID 30121937, 2019). "However, our studies also reveal that CHIP may potentially degrade tyrosine hydroxylase which would compromise the applicability of CHIP as a therapeutic approach for Parkinson's disease." (PMID 24664141, 2014). "In particular the verification of TH positive neurons in the appendix, together with the expression of several key molecules for pluripotency, make these cells enormously valuable for regenerative cell therapy in neurological disorders such as Parkinson’s disease." (PMID 24023797, 2013). "MPTP led to stronger akinetic parkinsonism and slower recovery in Ranbp2+/− than wild-type mice without viability changes of brain TH+-neurons of either genotype, with the exception of transient nuclear atypia via changes in chromatin condensation of Ranbp2+/− TH+-neurons." (PMID 22821000, 2012). "Chronic treatment of Parkinson’s disease mice with #11a markedly inhibits AEP activity and increasing TH-positive dopaminergic neurons." (PMID 40371638, 2025). "In a rat model of 6-OHDA-induced Parkinson’s disease, DHA exhibited neuroprotective benefits by enhancing tyrosine hydroxylase levels and improving motor function, including gait and posture." (PMID 41228449, 2025). "In vivo studies validated the efficacy of MT-treated hiPSC-derived DA progenitor cells in regenerating tyrosine hydroxylase (TH)-positive DA neurons and improving motor function in a MPTP-induced mouse model of Parkinson’s disease." (PMID 41422263, 2025). "In Parkinson’s disease, FTO knockout leads to a marked suppression of dopamine neuron death and restores the expression of tyrosine hydroxylase in the brains of PD mice." (PMID 39980685, 2025). "Specifically, we explore the effects of phosphodiesterase (PDE) inhibition and guanylate cyclase-C (GUCY2C) activation on tyrosine hydroxylase Ser40 phosphorylation and their impact on motor behavior in a 6-hydroxydopamine (6-OHDA) Parkinson's disease model." (PMID 39456033, 2024).
Parkinson disease (continued). "In order to further explore the pathological changes of Parkinson’s mouse, the DA content was detected by the HPLC and the mRNA and protein expression of TH were detected by PCR and WB." (PMID 38683404, 2024). "A previous study has shown that a reduction in TH, VMAT2, and DAT leads to dopamine depletion in substantial nigra of Parkinson’s disease patients." (PMID 37373089, 2023). "It has been reported that norlaudanosoline, detected in the urine of patients with Parkinson’s disease treated with L-3,4-dihydroxyphenylalanine (L-DOPA), reduces tyrosine hydroxylase activity during L-DOPA production." (PMID 36903413, 2023). "Still, as previously assumed, some researchers have supported the protective influence of NAC against induced parkinsonism, revealing that, several days after a severe oxidative insult, NAC can provide long-term neuroprotection of striatal TH fibers." (PMID 37371987, 2023). "Mn exposure also induces cellular damage through histone acetylation changes in neuronal PC2 cells, while in human neuroblastoma SH-SY5Y cells, Mn alters DNA methylation on TH, PARK2, and PINK1 genes that are vitally involved in the onset of Parkinsonism." (PMID 36142718, 2022). "In a 1-methyl-4-phenyl-1,2,3,6-tetrahydropyridine (MPTP)-induced mouse model of acute Parkinson's disease, HMGB1 can promote the expression of tyrosine hydroxylase (TH) in the striatum, thereby maintaining dopaminergic neuron function." (PMID 36388178, 2022). "CRYM, TH, and GBA were evaluated, as these genes have been shown to be differentially expressed in Parkinson’s models." (PMID 34358063, 2021). "Dystonia with parkinsonism includes DRD [DYT5, tyrosine hydroxylase (TH), and sepiapterin reductase (SPR)], dopamine agonist-responsive dystonia, rapid-onset dystonia parkinsonism (DYT12), and early-onset dystonia with parkinsonism (DYT16)." (PMID 32117556, 2019). "As an example, tyrosine hydroxylase, the first and rate-determining step in dopamine synthesis, is also substrate inhibited and could provide an alternative explanation for low dopamine production in Parkinson disease or for insufficient production of catecholamines in other cell types." (PMID 31357483, 2019). "Since dopamine-producing neurons are diminished in Parkinson's disease, one would expect a decrease in the endogenous concentration of L-DOPA, as it is a product of the metabolism of L-tyrosine by TH." (PMID 22316420, 2012). "We assessed the neuroprotective potential of vaccines containing tyrosine hydroxylase (a neuronal protein involved in dopamine synthesis) or Copaxone® in CFA in the 1-methyl-4-phenyl-1,2,3,6-tetrahydropyridine (MPTP) mouse model of Parkinson's disease." (PMID 21304945, 2011). "Noteworthy, TH, dopamine receptor 2 (DRD2), SLC6A3/DAT, SLC18A2, tubulin beta 2A (TUBB2A), tubulin alpha 4A (TUBA4A), and tubulin beta 3 (TUBB3) were the 7 key genes enriched in the Parkinson disease pathway." (PMID 40259945, 2025). "In a 1-methyl-4-phenyl-1,2,3,6-tetrahydropyridine (MPTP)-induced Parkinson’s disease mouse model, treatment with Lf-ASX-LPs resulted in 5.0-, 3.1-, and 5.6-fold increases in dopamine levels, TH+ fiber density, and TH+ neurons, respectively, restoring dopaminergic neuron damage." (PMID 39905399, 2025). "Consequently, these patients often present parkinsonism, dystonia and intellectual disablilities and treatment with the products of TPH2 and TH metabolism, 5-HTP and L-3,4-dihydroxyphenylalanine (L-DOPA), can ameliorate their symptoms." (PMID 39695187, 2024). "Furthermore, the stabilization of HIF-1α by Lf leads to the induction of tyrosine hydroxylase (TH) and several neuroprotective factors, thereby enhancing neuronal viability against MPP+ toxicity in Parkinson’s disease." (PMID 38731800, 2024).
Parkinson disease (continued). "Besides, the content of DA and the expression of TH both reduced in striatum of brain in MPTP treated mice, which indicated that the Parkinson’s mouse model was constructed successfully." (PMID 38683404, 2024). "Compound III stabilized TH in vitro and increased total TH activity in mouse brains, representing a valuable proof of concept for the potential of PCs as therapies for the treatment of THD and other parkinsonisms." (PMID 38813865, 2024). "In addition, tyrosine hydroxylase concentration decreases markedly after 6-OHDA injection, resulting in the model’s typical manifestation of Parkinson’s disease motor symptoms." (PMID 37270842, 2023). "Total TH expression and TH phosphorylation at Ser-40 in the RV and LV were analysed in control group, MPTP- or MPTP + L-DOPA-treated-animals to determine the impact of Parkinsonism and its treatment on the noradrenergic cardiac pathways." (PMID 34615910, 2021). "Chronic Δ9‐THCV dosing reduced microglial activation and preserved nigrostriatal dopaminergic neurons after 6‐OHDA application and in the LPS model of Parkinson's disease, Δ9‐THCV preserved TH positive neurons, mirroring the effects of the CB2 receptor agonist HU‐308." (PMID 32608035, 2020). "DAT‐ir axon length density in R does not correlate with the number of TH+ neurons, but does parallel the severity of parkinsonism: the more severe the condition, the higher the DAT‐ir axonal density in the R nucleus." (PMID 31800134, 2020). "By using a Dat driven Cre, Lmx1b was removed in postmitotic mdDA neurons, which led to dysregulation of the autophagic-lysosal pathway, abnormal synaptic responses and reduced protein levels of striatal TH and DAT expression, all processes that contribute to a Parkinson’s disease pathology." (PMID 30930745, 2019). "However, it is not clear if single allele mutation in TH modifies the susceptibility to the adult form of Parkinson disease (PD)." (PMID 20809526, 2010). "In modeling Parkinson’s disease with cerebral midbrain organoids, the specification of cells induces the expression of transcription factors FOXA1/2, LMX1A, and LMX1B in midbrain dopaminergic progenitor cells that are able to express tyrosine hydroxylase and produce dopamine." (PMID 34502516, 2021). "Previously, we demonstrated that SPKs differentiated into TH-positive neuron-like cells in vitro with intracellular delivery of VHL protein-derived peptide and that these transplanted cells functioned as dopaminergic neurons in the brain of Parkinson’s disease model rats." (PMID 29401731, 2018). "In addition to TH, Iba1 and GFAP immunohistochemistry, a range of different proteins involved in processes that may be impaired in Parkinson-GBA1 (such as autophagy, lysosomal functioning and endoplasmic reticulum stress) were analysed by western blotting." (PMID 28969384, 2017). "Our successful isolation of the new N27-A cell clone with expression of TH, DAT, VMAT2, dopaminergic transcription factors, dopaminergic storage protein, and functional dopamine synthesis and release, should provide an improved in vitro model of dopamine neurons for research on Parkinson’s disease." (PMID 27512998, 2016). "A case study using Parkinson disease (PD) has identified four candidate genes (UBB, SEPT5, GPR37 and TH) that ranked higher than our adaptive threshold, all of which are involved in the PD pathway." (PMID 21731658, 2011). "Moreover, A1 significantly increases the number of tyrosine hydroxylase-positive TH+ dopaminergic neurons in the CNS, particularly in the substantia nigra pars compacta (SNpc), but does not alter susceptibility to MPTP-induced parkinsonism." (PMID 39649680, 2024). "TH expression can also vary in neurons and can fall in Parkinson’s disease, but there are very few reports of neurons losing detecting TH staining while remaining live neurons, and as TH is required for dopamine synthesis, cells without TH can not be dopaminergic neurons." (PMID 34635136, 2021).
Parkinson disease (continued). "Despite its ability to express DBH in addition to TH, SH-SY5Y has widely been used to model dopaminergic neurons (which do not express DBH) to research Parkinson’s disease." (PMID 40071727, 2025). "Indeed, TH-staining constituted a relatively large proportion of the NRTN-immunohistochemical footprint, whereas there was a comprehensive loss of TH-positive fibres in areas without detectable NRTN staining similar to Parkinson’s disease controls, as we have previously reported." (PMID 32203581, 2020). "It demonstrated that 50 mg/kg/d GTB administration significantly protected nigral TH neurons as well as the striatal TH fibers against MPTP-insult and this protection was absent in MPTP-intoxicated animals fed with only vehicle, confirming the effect of GTB in parkinsonism in vivo." (PMID 36720111, 2022). "Quantitative evaluations of TH-immunoreactive fibres revealed densities ∼2–3 times greater with combined nigral and putamenal CERE120 delivery than putamen alone, which in turn was 1.3–1.8 times higher than in the Parkinson’s disease patients who did not undergo gene therapy." (PMID 32203581, 2020). "Stereological analyses revealed that densities of TH-positive neurons were 1.7–3.3 times higher with combined nigral and putamenal CERE120 delivery compared to putamen alone, which in turn was 0.49–0.68 times higher in comparison to Parkinson’s disease patients without gene delivery." (PMID 32203581, 2020).